EGF (epidermal growth factor)
Diseases named in the same sentence as EGF in open-access papers (continued):
Sharing a sentence is not in itself a finding about the gene and the disease.
astrocytoma (15 papers, 2000 to 2024). "EGF-associated pathways and angiopoietin 2 have been used as a point of differentiation between grade IV astrocytoma, i.e., glioblastoma multiform from lower-grade astrocytoma." (PMID 39796008, 2024). "Here we showed EGF had a significant effect on PN-1 up-regulation, which was once reported to up-regulate PN-1 in astrocytoma U373-MG cells." (PMID 31501409, 2019). "Other investigators have shown that EGF increases NRP-1 expression in human malignant astrocytoma cell lines and that the expression of NRP-1 mRNA peaks at 4 h and returns to basal levels 8 h after EGF treatment." (PMID 12618892, 2003). "Moreover, EGF was shown to be a potential ligand to overcome resistance during other RTK inhibitors in both low grade astrocytoma and ependymoma." (PMID 25799134, 2015). "Compound A suppressed the proliferation of astrocytoma cells by inhibiting ERK phosphorylation and epidermal growth factor-dependent activation of ERK signaling." (PMID 28405192, 2017). "Kasza and Koj found that EGF enhances uPA, tPA and PAI-1 expression in astrocytoma cells." (PMID 17261179, 2007).
diabetic nephropathy (15 papers, 2018 to 2025). "Therefore, we focused on the role of necroptosis in diabetic nephropathy (DN) and identified EGF, PAG1, and ZFP36 as potential biomarkers associated with necroptosis using the WGCNA algorithm." (PMID 37988198, 2023). "EGF also plays a vital role in the activation pathway that mediates podocyte damage and loss in diabetic nephropathy, and loss of the podocyte EGF receptor might mitigate diabetic nephropathy." (PMID 35059432, 2021). "Three necroptosis-related biomarkers, EGF, PAG1, and ZFP36, were identified and showed strong diagnostic ability for diabetic kidney disease." (PMID 37988198, 2023). "This study observed a downregulation of EGF in the context of diabetic nephropathy (DN), which is consistent with prior research indicating a reduction in urinary EGF levels associated with a decline in glomerular filtration rate (GFR) among DN patients." (PMID 37988198, 2023). "Earlier investigators have shown that there was a positive correlation between urine EGF with eGFR in primary GN, diabetic nephropathy, and an inverse correlation with the degree of tubulointerstitial chronicity in primary GN." (PMID 35271583, 2022). "Only one study aimed to assess EGF in serum and revealed higher EGF levels in patients with diabetic kidney disease as compared with patients free of this complication." (PMID 31936869, 2020). "Urinary EGF was examined in a large cohort of 642 type 2 diabetic people to investigate its relationship with diabetic kidney disease." (PMID 31936869, 2020). "Increased monocyte chemoattractant protein-1 (MCP-1) and decreased epidermal growth factor (EGF) are promising biomarkers to predict progressive decline in kidney function in non-diabetic kidney diseases." (PMID 30241508, 2018). "Earlier studies have shown that combinations of EGF with MCP-1 in the form of EGF/MCP-1 ratio was a better predictor of eGFR decline in non-diabetic kidney disease compared to either biomarker alone." (PMID 30241508, 2018). "Previous investigations reported that urinary EGF holds promise as a valuable biomarker that reflects disease activity across various kidney disorders, including lupus nephritis, diabetic kidney disease, IgA nephropathy, and autosomal dominant polycystic kidney disease." (PMID 38732362, 2024). "A study on mice demonstrated that EGF might be involved in diabetic kidney disease development as it is a growth factor also produced locally in distal tubular cells and it plays a significant role in the repair and regeneration of renal tubules." (PMID 31936869, 2020). "There is no study evaluating an association between serum EGF and diabetic kidney disease." (PMID 31936869, 2020). "In clinical settings, the urinary excretion of EGF has shown to be decreased in a wide range of kidney pathologies—e.g., diabetic nephropathy and IgA nephropathy—suggesting that it could potentially work as a biomarker of a pathway which is common to several kidney tissue insults." (PMID 31614925, 2019). "EGF has gained interest as a biomarker of renal disease because its decreased urinary excretion has been observed in nearly all rodent kidney injury models and in various human kidney diseases, including diabetic nephropathy, IgA nephropathy, and lupus nephritis." (PMID 31614925, 2019). "Bioinformatics and experimental validation have thus identified EGF and PAG1 as necroptosis-related biomarkers for diabetic nephropathy." (PMID 37988198, 2023). "We aimed to evaluate the performance of urinary EGF, MCP-1 or their ratio in predicting rapid decline of GFR in a cohort of Type 2 diabetic patients (T2DM) with diabetic kidney disease (DKD)." (PMID 30241508, 2018). "EGF and UMOD are two urine biomarkers that we found predict progression of diabetic kidney disease." (PMID 40548378, 2025).
diabetic nephropathy (continued). "Another hint for activating the potentially protective HIF signal was the recently demonstrated renal preservation of another HIF-mediated gene, epidermal growth factor (EGF), in patients on SGLT2is, which was found to correlate with a slower progression of diabetic kidney disease." (PMID 39409086, 2024). "Furthermore, both urinary EGF and MCP-1 have been studied extensively in the setting of diabetic kidney disease, and both lower urinary EGF and higher MCP-1 are significantly associated with greater disease progression." (PMID 33974569, 2021). "The results strongly indicate that in T1DM, serum EGF concentration might serve as a useful marker to detect microangiopathy, while GDF-15 may probably be engaged to some extent in microvascular damage as a marker of diabetic kidney disease, peripheral neuropathy, and retinopathy." (PMID 31936869, 2020).
meningioma (15 papers, 2010 to 2024). A generally slow growing tumor attached to the dura mater. "Other growth factors such as platelet-derived growth factor (PDGF) and epidermal growth factor (EGF) also have increased expression in meningioma, and stand as possible future therapeutic targets." (PMID 34638590, 2021). "Receptor activation of epidermal growth factor (EGF) or transforming growth factor-a (TGF-a) can promote in vitro proliferation of meningiomas cells." (PMID 32974188, 2020). "Our study identified two different ligands of EGFR, amphiregulin (AREG) and heparin-binding EGF (HB-EGF) that are elevated in the sera of Grade I meningioma patients." (PMID 31649887, 2019). "Ratio distribution of PE for VEGF and EGF between different sections of four meningiomas and a LMBC tumor was provided." (PMID 31565199, 2019). "In the present study we have demonstrated that EGFR and its ligands EGF and TGFα are widely expressed in human meningiomas and that the receptor appears to be in an activated state." (PMID 28367377, 2017). "We also presented evidence that EGFL6, a secreted protein, belonging to the epidermal growth factor (EGF) repeat superfamily, was overexpressed in benign meningioma tissues and serum." (PMID 23285163, 2012). "Results also revealed that EGF (100 ng/mL, 48 h), an agonist of EGFR signaling, could remarkably upregulate PD‐L1 protein expression in NF2‐associated meningioma cells, demonstrating that EGF can induce an increase in PDL1 expression." (PMID 38828669, 2024). "Several growth factors, including vascular endothelial growth factor (VEGF), platelet-derived growth factor (PDGF), and epidermal growth factor (EGF), and their associated receptors are overexpressed in meningiomas, which stimulates tumor growth and progression in such tumors." (PMID 33330036, 2020). "However, the aim of the present work was to explore the status of PE in VEGF and EGF in different regions of the meningioma tumor samples to trace diversity and evidences of an evolutionary event within the tumor’s regions." (PMID 31565199, 2019). "Conclusively, higher expression pattern of VEGF than EGF may play an important role in the heterogenic nature of meningioma of tumor progression in peripheral section." (PMID 31565199, 2019). "Therefore, we aimed to explore the PE of VEGF and EGF in meningiomas by considering evolutionary strategy and the regional tumor-based assay." (PMID 31565199, 2019). "As key downstream effector cells, macrophages and monocytes also exhibited the properties of source cells in epidermal growth factor (EGF) and resisting signaling, interacting with meningioma or immune cells." (PMID 36994665, 2023). "It is worthy noting that meningioma cells are capable of autocrine expression of the EGFR ligands, such as TGF-α and EGF." (PMID 37171006, 2023). "Similar to other neoplasms, meningiomas often overexpress VEGF, PDGF, EGF, and other growth factor receptors." (PMID 33330036, 2020). "Compared to the control group, Grade I meningioma patients showed increased serum levels of amphiregulin (AREG), CCL24, CD69, prolactin, EGF, HB-EGF, caspase-3, and decreased levels of VEGFD, TGF-α, E-Selectin, BAFF, IL-12, CCL9, and GH." (PMID 31649887, 2019). "Similarly, the epidermal growth factor receptor (EGFR), and both their EGF and transforming growth factor-alpha (TGFα) ligands, as well as some members of the insulin-like growth factor (IGF) system (e.g. IGF2), have all been associated with meningioma cell proliferation and tumor progression." (PMID 25965831, 2015). "The authors speculate that activation of EGFR is not a result of any mutations of the EGFR, but it is secondary to autocrine/paracrine stimulation by their endogenous ligands, EGF and TGF alpha, which are also expressed in meningiomas and may contribute to meningothelial cell proliferation." (PMID 20509969, 2010).
cardiac hypertrophy (14 papers, 2007 to 2025). "Another important finding is that cardiac hypertrophy mediated by EGFR activation is Ang II‐independent, as demonstrated by the fact that EGF stimulation alone induced cardiac hypertrophy in H9c2 cells." (PMID 26762600, 2016). "Growth factors such as EGF activate p85α, enhancing protein synthesis essential to cardiac hypertrophy." (PMID 22200760, 2012). "Given the known role of the EGF MAPK pathway in cardiac hypertrophy, this altered methylation of the BTC gene may yet again represent a mechanism by which the observed benefits of EV treatment may be explained." (PMID 37982029, 2023). "EGF is involved in endothelial dysfunction, neointimal hyperplasia, cardiac hypertrophy and remodeling and, as shown by us, reduction in circulating levels of EGF could be involved in the ticagrelor-mediated improvement of endothelial function in stable CAD/COPD patients." (PMID 32106619, 2020). "Cardiac hypertrophy can be induced by treating ventricular myocytes with a wide variety of stimuli, ranging from GPCR agonists like endothelin-1 (ET1) and PE to receptor tyrosine kinase agonists such as epidermal growth factor (EGF)." (PMID 17726532, 2007). "Though several studies demonstrated a role for EGFR-dependent signaling in cardiac hypertrophy and EGFR inhibitors attenuated organ deterioration, our findings indicate that systemic EGF and EGFR display no specificity for PH and RVH." (PMID 35053115, 2022).
Sepsis (14 papers, 2012 to 2025). Sepsis is defined as life-threatening organ dysfunction caused by a dysregulated host response to infection. "For instance, EGF represents tissue recovery or regeneration after injury and is associated with cellular proliferation and survival in sepsis." (PMID 33509215, 2021). "HGF and IL-1RA demonstrated diagnostic capability, and EGF predicted favorable prognosis among sepsis patients." (PMID 31583025, 2019). "For EGF, we hypothesize that tissue recovery or regeneration by growth factors might be associated with prognosis of sepsis." (PMID 31583025, 2019). "In cases of sepsis, urinary EGF was low and serum creatinine high, and urinary EGF increased simultaneously with a decrease in serum creatinine." (PMID 38732362, 2024). "Adding a small amount of EGF to sepsis or healthy sera enhanced human keratinocyte migration significantly." (PMID 34939229, 2022). "In our previous in vitro study, we found lower levels of EGF in sepsis sera, and keratinocyte monolayer wounds treated with sepsis sera had decreased keratinocyte migration and proliferation compared with healthy sera." (PMID 34939229, 2022). "As expected, all of the cytokines were increased in the sepsis group compared to the healthy control group, except for EGF, which was lower in the sepsis group." (PMID 31583025, 2019). "In an experimental mouse model of sepsis triggered by cecal ligation and puncture, systemic administration of EGF improved intestinal integrity and decreased mortality." (PMID 31583025, 2019). "Further, intestine-specific overexpression of EGF in transgenic mice also improves gut integrity and improves survival, demonstrating that targeting gut epithelial integrity is a novel pre-clinical therapeutic approach towards improving outcomes in sepsis." (PMID 40098052, 2025). "Moreover, administration of EGF to septic mice has been shown to lessen the severity of sepsis, even in alcohol-fed mice, in part by protecting gut barrier function." (PMID 37786945, 2023). "As EGF was the only molecule that was included in the multivariate analysis, EGF reflects prognosis and might play an important role in the pathogenesis of sepsis." (PMID 31583025, 2019). "For example, epidermal growth factor (EGF) has been shown to improve gut apoptosis, proliferation, and permeability following either cecal ligation and puncture or Pseudomonas pneumonia even if started 24 h after the onset of sepsis." (PMID 30923621, 2019). "Except for EGF, concentrations of the molecules were increased in the sepsis group." (PMID 31583025, 2019). "Notably, systemic treatment with EGF improves survival following pre-clinical sepsis." (PMID 40098052, 2025). "Epidermal growth factor is a cytoprotective polypeptide, and mice administered with systemic epidermal growth factor, as well as those with enterocyte-specific overexpression of epidermal growth factor, display improved intestinal barrier function and survival following sepsis." (PMID 34712743, 2021). "However, systemic epidermal growth factor has been shown to prevent sepsis-induced mortality and gut apoptosis in an intestine-dependent fashion following either peritonitis or Pseudomonas aeruginosa pneumonia and thus represents a potential therapeutic agent in radiation combined injury." (PMID 24204769, 2013). "In our previous in vitro study, we found out that a keratinocyte cell line treated with sepsis sera had diminished migration, proliferation and viability compared with keratinocytes treated with healthy sera, and one possible reason could be the decreased levels of epithelial growth factor (EGF)." (PMID 34939229, 2022). "A recent Olink study also found that EGF levels were lower and IL-15 levels higher in children with more severe Multiple Organ Dysfunction (MOD), whether due to sepsis or not." (PMID 39264477, 2024).
breast adenocarcinoma (13 papers, 1992 to 2024). "Additionally, we found that MVK suppressed EGF-induced phosphorylation of PI3K and Akt in MDA-MB-231 human breast adenocarcinoma cells and in human small airway epithelial cells." (PMID 38272219, 2024). "Surprisingly, the rat mammary adenocarcinoma MTLn3 cells as well as the three TNBC cell lines studied were not attracted to EGF." (PMID 36584207, 2022). "Like cell proliferation, cell invasion can be stimulated by EGF, not just in cytotrophoblasts but also in carcinoma cells, such as breast adenocarcinoma MDA-MD-231 and colon adenocarcinoma HCT-8/E11 cells." (PMID 35054855, 2022).
Cognitive impairment (13 papers, 2014 to 2025). Abnormal cognition is characterized by deficits in thinking, reasoning, or remembering. "The concentration of EGF in plasma increased in patients with mild cognitive impairment and Alzheimer’s disease." (PMID 38649851, 2024). "The relationship between serum EGF and cognition in PD patients was analyzed, and it was concluded that serum EGF levels were negatively correlated with the occurrence of cognitive impairment." (PMID 36383265, 2023). "In view of the opposite changes of NRG1/ErbB4 and EGF/ErbB1, the expression of hippocampal NRG1/ErbB4 seems to be more directly linked with cognitive deficits in CCH." (PMID 29875654, 2018). "Regarding the potential function of EGF, a previous study showed that EGF treatment prevented cognitive impairment in mice, which is consistent with the hypothesis that a loss of EGF signaling contributes to AD83." (PMID 40683902, 2025). "Conversely, CBLB downregulation may disruptproteasome-mediated protein degradation, immune regulation and the EGF pathway, potentially leading to cognitive deficits and synapticdysfunction." (PMID 40162448, 2024). "EGF is essential in memory recovery and reduction of cognitive impairment in multiple AD models." (PMID 36981618, 2023). "Abrogation of EGF signaling could be a possible explanation of how periodontal pathogens could potentially induce cognitive impairment." (PMID 36981618, 2023). "Additionally, EGF was recently shown to be over-expressed in those with mild cognitive impairment (MCI) or AD compared to healthy controls." (PMID 24495355, 2014). "In this regard, quetiapine promoted ERK mediated neurite sprouting in PC12 cells with improvements in affect and mood also ascribed to ERK signaling, and in mouse cortex prevented cuprizone induced myelin breakdown and cognitive impairments via ERK dependent on EGF." (PMID 24552586, 2014). "However, it is still unclear whether the effects of EGF signaling abrogation by periodontitis elicit cognitive impairment through these signaling molecules or through different EGF dependent pathways." (PMID 36981618, 2023). "BBCT significantly improved cognitive impairment in a BCAS mouse model by inhibiting microglial and astrocyte activation and regulating the expression of CDC20, EGF, TRAF1, and key proteins in the neuroactive ligand-receptor interaction and neuropeptide signaling pathways." (PMID 38464836, 2024).